CRP (C-reactive protein)
Diseases named in the same sentence as CRP in open-access papers (continued):
Sharing a sentence is not in itself a finding about the gene and the disease.
schizophrenia (continued). "Those with high CRP at age 15/16 years compared with those with low CRP had over four times the odds of schizophrenia by age 27 years (adjusted OR 4.25; 95% CI, 1.30–13.93)." (PMID 27622678, 2017). "The association between CRP and schizophrenia remained after excluding this participant; the adjusted OR for schizophrenia by age 27 years for each SD increase in CRP level at age 15/16 years was 1.22 (95% CI, 1.02–1.45)." (PMID 27622678, 2017). "Nonetheless, inflammatory processes appear to play a key role in schizophrenia, and CRP has been widely regarded as a state marker in schizophrenia alongside other cytokines like tumor necrosis factor-alpha." (PMID 29404313, 2017). "In the leave-1-out MR analyses using the liberal CRP set, all OR estimates of schizophrenia per 2-fold increment in circulating CRP levels were directionally consistent." (PMID 29094161, 2017). "Five participants with baseline serum CRP levels >1 mg/L at age 15/16 years developed schizophrenia by age 27 years." (PMID 27622678, 2017). "Odds ratio estimates of schizophrenia per 2-fold increment in circulating CRP levels based on the ratio method ranged from 0.90 (95% CI, 0.79-1.02) to 0.97 (95% CI, 0.84-1.12)." (PMID 29094161, 2017). "Though limited by a relatively small sample size and the unavailability of longitudinal data, the correlation between CRP and psychopathology in this sample of patients supports a role for inflammation in the pathophysiology of schizophrenia." (PMID 29404313, 2017). "In stratified analyses, the OR for schizophrenia by age 27 years for each SD increase in serum CRP levels at age 15/16 years was 1.22 (95% CI, 1.02–1.46) for men, and 1.21 (95% CI, 0.91–1.62) for women." (PMID 27622678, 2017). "Meta-analyses have shown that inflammatory markers such as tumor necrosis factor α (TNF-α) and C-reactive protein (CRP) are elevated in both schizophrenia and bipolar disorder." (PMID 28039552, 2017). "Using CRP as a categorical variable, those with high (>3 mg/L) compared with low (<1 mg/L) CRP levels at baseline were more likely to develop schizophrenia; adjusted OR 4.25 (95% CI, 1.30–13.93)." (PMID 27622678, 2017). "Among the different inflammatory markers, CRP holds a prominent position in severe psychiatric conditions, and particularly in schizophrenia." (PMID 27547191, 2016). "The objective of the present study was to test if physical functional capacity in patients with schizophrenia correlates with common inflammatory markers, such as CRP and Von Willebrand factor (VWF)." (PMID 27547191, 2016). "One could speculate that CRP-interferon pathways may induce neuroprotection by contributing to glutamate clearance, leading to the protection of neurons against the oxidative stress associated with an excess of glutamate, and thereby offering a protective effect against schizophrenia." (PMID 27327646, 2016). "We further aimed to confirm the identified association between CRP and schizophrenia using a CRP polygenic risk score (CRPPRS) from individual-level genotype data from the largest consortium of schizophrenia to date." (PMID 27327646, 2016). "In summary, the present study revealed an association between impaired physical functional capacity and increased CRP inflammatory marker in patients with schizophrenia, a complex condition with both physical and mental consequences." (PMID 27547191, 2016). "When incorporating 18 genome-wide CRP-associated SNPs using individual-level data, we confirmed a modest, but significant, protective effect of CRP level for schizophrenia." (PMID 27327646, 2016). "Raised levels of the inflammatory marker CRP, which is pathogenic in the development of CVD, have been described in both schizophrenia and bipolar affective disorder." (PMID 27000113, 2016). "In a 2014 review, Singh analyzed the current evidence for the role of CRP in schizophrenia, identifying increased CRP in 14 of 16 studies." (PMID 27547191, 2016).
schizophrenia (continued). "The aim of this study was to investigate the relationship between quality of life (QoL) and chronic inflammation assessed using C -Reactive Protein (CRP) in patients with schizophrenia." (PMID 26041435, 2015). "Currently, however, no study has specifically investigated the relationship between impaired QoL and elevated CRP levels in patients with schizophrenia." (PMID 26041435, 2015). "The aim of this study was to investigate the relationship between QoL and chronic inflammation assessed using CRP in patients with schizophrenia, in addition to considering key socio-demographic and clinical confounding factors." (PMID 26041435, 2015). "Our results confirm reports from previous studies showing that CRP level is increased in schizophrenia patients, including drug-naïve individuals." (PMID 25214388, 2015). "This is in line with a recent study in patients with schizophrenia, in which both high CRP values and HSV1 antibodies predicted cognitive functioning." (PMID 24983885, 2014). "This corroborates a recent study that reported serum CRP levels are increased more in schizophrenia patients who had taken typical APs as compared to those who had taken atypical APs." (PMID 19758435, 2009). "Among them, the higher OR values of IL-6 and CRP suggested that they might be the core driving factors for the occurrence of MS in patients with schizophrenia." (PMID 41450839, 2025). "Although a number of studies have consistently reported elevated CRP levels in schizophrenia patients compared to healthy controls the significance of this finding remains unclear." (PMID 40980040, 2025). "Therefore, in this study, we aimed to clarify the effect of perceived family support on inflammatory processes, as measured by CRP levels, among patients with schizophrenia." (PMID 40724779, 2025). "In addition, elevated CRP levels and BMI were documented in adults with schizophrenia and a history of childhood maltreatment." (PMID 40724779, 2025). "Notably, this study sought to clarify the effect of perceived family support on CRP levels among patients with schizophrenia." (PMID 40724779, 2025). "Studies have shown that patients with schizophrenia exhibitelevated levels of monocytes, neutrophils, and C-reactive protein (CRP).Additionally, various cytokines (e.g., monocyte chemoattractant protein-1,IL-1β, IL-5, IL-6, IL-9 and TNF-α) have been reported to beupregulated in schizophrenia." (PMID 40926813, 2025). "Therefore, the purpose of this study was to explore the interrelations between CRP, BMI and perceived family support among individuals with schizophrenia in outpatient treatment." (PMID 40724779, 2025). "Furthermore, a meta-analysis involving five studies exploring cytokine levels in chronic schizophrenia patients disclosed that 28% of these patients manifested elevated CRP levels." (PMID 39273641, 2024). "Furthermore, there is a noteworthy link between schizophrenia and elevated pro-inflammatory factors, such as C-reactive protein (CRP) and NLR." (PMID 39502297, 2024). "Interestingly, further cognitive alterations were linked to reduced CRP levels, emphasizing the complex interaction of inflammation, CRP, and cognitive function in schizophrenia." (PMID 39273641, 2024). "There are several factors can affect HsCRP levels, including elevated CRP levels associated with negative symptoms of chronic schizophrenia, as well as some antipsychotic medications." (PMID 37728803, 2024). "In the context of schizophrenia, researchers have found evidence of cytokines such as C-reactive protein (CRP), IL-1β, IL-6, IL-12, interferon-γ, and tumor necrosis factor α (TNF-α) being associated with endophenotypes and varying disease status of schizophrenia." (PMID 38445386, 2024).
schizophrenia (continued). "Elevations in peripheral inflammatory proteins, particularly blood cytokine levels, are consistently reported in schizophrenia; these include interleukin (IL)-1β, IL-1 receptor antagonist, soluble interleukin-2 receptor, IL-6, IL-8, IL-10, tumor necrosis factor-α, and C-reactive protein." (PMID 39334950, 2024). "However, C-reactive protein in plasma differed in the schizophrenia group, i.e. 1.2 in this cohort compared to 4.1 in the original cohort." (PMID 39350952, 2024). "In the current study, CRP was higher in the schizophrenia group as compared to the HC group." (PMID 37763110, 2023). "Therefore, in this study, we compared serum levels of CRP, vitamin D, and its related markers in patients with various forms of acute psychosis (schizophrenia, bipolar disorder, and methamphetamine-induced psychosis) with a healthy control group." (PMID 37803327, 2023). "The effect of CRP on schizophrenia has been well-researched." (PMID 37763110, 2023). "As for some potential confounders such as CRP and educational attainment and vitamin D levels, there are some evidences to manifest AA-related SNPs would not affect the schizophrenia risk through these traits." (PMID 36904193, 2023). "CRP has also previously been associated with cognitive impairment severity in schizophrenia patients but not with the severity of psychiatric symptoms." (PMID 37032951, 2023). "A single-photon emission computed tomography (SPECT)-based study of brain perfusion in patients with schizophrenia revealed greater perfusion of the left amygdala in patients with hs-C-reactive protein levels ≥ 3 mg/L than in patients with hs-C-reactive protein levels < 3 mg/L." (PMID 37848831, 2023). "Other data show that schizophrenia CRP levels mainly correlate with severity, and during the recrudescent phase, they seem higher when catatonic features, negative symptomatology, and aggressiveness are related; it has not been shown to be correlated to suicidal behavior and ideation." (PMID 37873776, 2023). "The findings add validity of a neurodevelopmental subtype of schizophrenia identified by comparing estimated premorbid and current IQ and characterised by smaller premorbid brain volume and higher measures of low-grade inflammation (CRP)." (PMID 35177144, 2023). "The prevalence of elevated CRP levels in patients with schizophrenia was 28%." (PMID 35546942, 2022). "Previous literature has shown that serum CRP levels were significantly increased in schizophrenia patients compared to the healthy population and could predict glucolipid metabolism disorders in patients." (PMID 36090349, 2022). "Signs of a peripheral inflammatory response in schizophrenia are indicated by elevated serum/plasma levels of certain pro-inflammatory factors, including prostaglandin E2 and C-reactive protein, as well as some pro-inflammatory cytokines, such as IL-1β, IL-6, IL-8, and tumor necrosis factor-α." (PMID 35722585, 2022). "In schizophrenia, soluble PRRs (CRP, sCD14, etc.)have been well studied." (PMID 35546942, 2022). "In our study, CRP levels were higher in more old patients with chronic schizophrenia, while a recent meta-analysis showed that CRP levels did not change between the first episode of psychosis and with progression of schizophrenia." (PMID 35873262, 2022). "Using CRP as a biomarker of peripheral inflammation in persons with schizophrenia may help to identify vulnerable patients and those that may benefit from adjunctive anti-inflammatory treatments." (PMID 35873262, 2022). "Several meta-analyses have confirmed that blood CRP levels are elevated in schizophrenia." (PMID 35546942, 2022). "However, one cell surface receptor mRNA, TNFR2, was increased even in people with schizophrenia with ‘normal’ levels of IL-1β mRNA and CRP relative to low inflammation controls." (PMID 35027554, 2022).
schizophrenia (continued). "Indeed, increased serum concentrations of C-reactive protein (CRP), a peripheral marker of inflammation, were associated with worse cognitive performance in patients with schizophrenia." (PMID 35625833, 2022). "CRP levels are elevated in blood of patients with schizophrenia." (PMID 35546942, 2022). "A linear regression established that the first episode vs. multiple episodes of schizophrenia could statistically significantly predict personal and social performance and cognition, including speech fluency and planning, as well as CRP levels." (PMID 35873262, 2022). "A number of studies among patients with first episode and persistent or recurrent schizophrenia have shown increased serum levels of acute phase proteins, such as CRP, and proinflammatory markers such as tumor necrosis factor (TNF-alpha), IL-6, and IL-1β, although with some inconsistency." (PMID 34465310, 2021). "The association of CRP with schizophrenia (Outlier-Corrected IVW β=-0.11; SE 0.03) was preserved in MR-PRESSO outlier-corrected IVW analysis, but the associations of trans variants for sIL-2Rα and BDNF with schizophrenia attenuated." (PMID 34280516, 2021). "In addition, syncytin-1 expression is elevated in neuropathological disorders such as schizophrenia (SZ) and bipolar disorder (BD) while positively correlated with C-reactive protein (CRP) levels, an inflammation indicator." (PMID 35059135, 2021). "From analyses of cis variants, each SD increase in genetically-predicted levels of sIL-2Rα (Wald Ratio OR=1.07; 95% C.I., 1.01-1.12) increased schizophrenia risk, while each SD increase in levels of CRP (IVW OR=0.93; 95% C.I., 0.88-0.99) decreased schizophrenia risk." (PMID 34280516, 2021). "Besides, many cross-sectional studies reported that proinflammatory cytokines and C-reactive protein (CRP) were increased in schizophrenia compared with healthy control (HC)." (PMID 34306006, 2021). "This pattern of results indicates that CRP, and hence IL-6 classic signalling, is unlikely to be the main “causal driver” of schizophrenia risk." (PMID 34280516, 2021). "Therefore, this study aimed to investigate the serum level of inflammatory markers (CRP and IL-6) among patients with schizophrenia." (PMID 34465310, 2021). "Multiple studies have reported an elevated CRP level in different stages of schizophrenia, indicating its potential to be used as a viable biomarker in the diagnosis and monitoring of schizophrenia along with assessing treatment response to conventional and non-conventional treatment regimens." (PMID 34884840, 2021). "Third, we show that the previously reported protective effect of CRP on schizophrenia could be explained by IL-6, an upstream inducer of CRP production." (PMID 34280516, 2021). "Similarly, high levels of C-reactive protein in schizophrenia suggest a role of inflammation in the pathogenesis of this psychopathology." (PMID 32300314, 2020). "Interestingly, CRP has shown to be protective of schizophrenia in MR studies, however, the GWAS studies included in previous MR research measured phenotypic markers in adults." (PMID 32828613, 2020). "There was also trend level evidence for an association between PRS-schizophrenia and CRP (β = 0.05; 95% CI, −0.01–0.10, p = .061) but not with IL-6 (β = 0.01; 95% CI, −0.04-0.09, p = .670)." (PMID 32828613, 2020). "Additionally, a large longitudinal study performed in Finland found an association between high-level C-reactive protein (CRP) values and the development of schizophrenia." (PMID 32513294, 2020). "•This potential protective effect of CRP has also been found for schizophrenia." (PMID 32473944, 2020). "It is also not known if the association between immunological markers (CRP or cytokines) and agitation is present in other diagnostic group than psychosis or schizophrenia." (PMID 31509578, 2019).
schizophrenia (continued). "Cross-sectional studies have linked inflammatory parameters in the blood, including C-reactive protein as well as interleukin-6 and interleukin-8, to severity of negative symptoms and cognitive performance in schizophrenia patients." (PMID 31354535, 2019). "Moreover, individuals with higher levels of inflammatory markers, including ESR (erythrocyte sedimentation rate) and CRP (C-reactive protein), were more likely to develop schizophrenia." (PMID 31908647, 2019). "Studies and meta-analyses showing increased levels of pro-inflammatory cytokines and CRP, for example, indicate that the development of some psychiatric disorders, including MD and schizophrenia, may involve inflammation." (PMID 31214060, 2019). "In this study, serum OXT, OXT receptor (OXTR), interleukin-6 (IL-6), high sensitivity CRP (hsCRP) and homocysteine (Hcy) levels were measured in 52 first-episode schizophrenia (FES) patients and 41 healthy controls (HC) from the Second Xiangya Hospital of Central South University." (PMID 31024366, 2019). "In a Finnish longitudinal cohort study higher CRP in adolescence was associated with increased risk of schizophrenia, but not ONAP, in adulthood." (PMID 29622048, 2019). "Population-based longitudinal studies have reported associations of elevated concentrations of CRP, IL-6 and erythrocyte sedimentation rate (ESR) in childhood, adolescence or young adulthood with risk of psychotic symptoms or diagnosis of schizophrenia subsequently in adulthood." (PMID 31563954, 2019). "Thus, a substantial proportion of chronically ill patients with schizophrenia display elevated peripheral inflammation markers and CRP in particular." (PMID 30364161, 2018). "One recent meta-analysis has concluded that increased CRP levels were associated with positive but not negative symptoms in schizophrenia." (PMID 30190688, 2018). "For instance, CRP was elevated in the serum of patients with schizophrenia and MS." (PMID 30245643, 2018). "The Schizophrenia subjects showed statistically significant increased hs-CRP values." (PMID 30190688, 2018). "Except for antipsychotic effects, no longitudinal data has suggested if increased CRP levels were associated with poor prognosis and outcomes in schizophrenia (including hospitalizations, accelerated cognitive impairment and functioning)." (PMID 30190688, 2018). "CRP is associated with increased mortality risk but not with the risk of rehospitalization in patients with depression, bipolar disorder or schizophrenia." (PMID 30483163, 2018). "One study conducted by the group of Brian Miller at Augusta University in Georgia, plans to randomize 30 stable outpatients with schizophrenia or schizoaffective disorder with CRP >5 mg/L to adjunct treatment with siltuximab which is a recombinant IL-6 monoclonal antibody, or placebo." (PMID 30766494, 2018). "To conclude, the acute phase protein CRP is elevated in a proportion of individuals with schizophrenia and other psychoses, the measure is reliable and widely available, and it has been found to correlate both with positive symptoms of schizophrenia and cognitive function." (PMID 30766494, 2018). "In relation to elevated CRP, there was a significant difference between the proportions of chronically ill patients with schizophrenia (43%) and healthy controls (20%) who could be classified as having elevated levels of inflammation." (PMID 30364161, 2018). "Besides its potential function as a biomarker for schizophrenia, CRP is also synthesized by hepatocytes under the regulatory control of IL-6, released by macrophages and adipocytes." (PMID 29434554, 2018). "We assessed the proportions of patients displaying a marker of inflammation (CRP) in two independent samples (in chronically ill patients with schizophrenia and over repeated admissions in patients experiencing an acute psychotic episode) and the ability of CRP to predict cortical thickness." (PMID 30364161, 2018).